KRTAP10-11 (keratin associated protein 10-11)
Description:
In the hair cortex, hair keratin intermediate filaments are embedded in an interfilamentous matrix, consisting of hair keratin-associated proteins (KRTAP), which are essential for the formation of a rigid and resistant hair shaft through their extensive disulfide bond cross-linking with abundant cysteine residues of hair keratins. The matrix proteins include the high-sulfur and high-glycine-tyrosine keratins.
Synonyms: KAP10.11; KRTAP18-11; KRTAP18.11; KAP18.11
Tractability: No criterion of Open Targets' tractability assessment is met for any kind of drug.
Gene: Protein-coding gene on chromosome 21 (44,646,414 to 44,647,650, forward strand). Ensembl gene ENSG00000243489.
Pathways (Reactome):
Developmental Biology: Keratinization
Gene Ontology:
Molecular function: protein binding
Cellular component: cytosol; keratin filament
Genetic constraint (gnomAD): Loss-of-function variants: 2 observed, 1.11 expected, observed/expected ratio (o/e) 1.8, 90% interval 0.5 to 1.93. That is too few expected variants to judge how well the gene tolerates losing a copy. Missense variants: 401 observed, 385.05 expected, observed/expected ratio (o/e) 1.04, 90% interval 0.96 to 1.13. Synonymous variants: 188 observed, 162.92 expected, observed/expected ratio (o/e) 1.15, 90% interval 1.02 to 1.3.
Homologues: Orthologues: chimpanzee KRTAP10-11 (96% identical), rat LOC120098854 (61% identical), rat Krtap10-1 (59% identical), rat Krtap10-9 (59% identical), mouse Krtap10-32 (55% identical), mouse Krtap10-30 (54% identical), mouse Krtap10-33 (54% identical), rat Krtap10-1l1 (54% identical), mouse Krtap10-23 (54% identical), mouse Gm49918 (54% identical), mouse Krtap10-21 (54% identical), mouse Krtap10-25 (54% identical), and 36 more. Paralogues in human: KRTAP10-9 (84% identical), KRTAP10-7 (80% identical), KRTAP10-6 (79% identical), KRTAP10-4 (78% identical), KRTAP10-5 (76% identical), KRTAP10-2 (74% identical), KRTAP10-1 (69% identical), KRTAP10-10 (69% identical), KRTAP10-12 (64% identical), KRTAP10-3 (64% identical), KRTAP10-8 (61% identical), KRTAP16-1 (34% identical), and 35 more.